KHSRP (KH-type splicing regulatory protein)
Diseases named in the same sentence as KHSRP in open-access papers (continued):
Sharing a sentence is not in itself a finding about the gene and the disease.
gastric cancer (5 papers, 2019 to 2025). A primary or metastatic malignant neoplasm involving the stomach. "KHSRP is highly expressed in gastric cancer tissues and is closely associated with malignant progression." (PMID 39866240, 2025). "Gain- and loss-of-function experiments were conducted to assess KHSRP’s effects on gastric cancer cell proliferation, stemness, and migration." (PMID 39866240, 2025). "Its overexpression is associated with poor prognosis, making KHSRP a potential prognostic marker and therapeutic target in gastric cancer." (PMID 39866240, 2025). "In summary, these results suggest that KHSRP is significantly overexpressed in gastric cancer and is associated with reduced survival, implicating its role in the progression of the malignant phenotype in gastric cancer." (PMID 39866240, 2025). "Furthermore, increased KHSRP expression was associated with poorer histological differentiation and more advanced clinical stages of gastric cancer." (PMID 39866240, 2025). "In Epstein–Barr virus (EBV)-associated gastric cancer, the interaction between KH-type splicing regulatory protein (KHSRP) and the EBV-encoded circLMP2A enhances KHSRP-mediated degradation of von Hippel–Lindau mRNA, resulting in the accumulation of HIF1α under hypoxic conditions." (PMID 40290118, 2025). "KHSRP acts as an oncogene in gastric cancer by promoting tumorigenesis and suppressing anti-tumor immune responses." (PMID 39866240, 2025). "In vitro experiments demonstrated that KHSRP silencing significantly inhibited the migration and invasion of gastric cancer cells, likely by disrupting their stemness." (PMID 39866240, 2025). "To verify the expression level of KHSRP protein in gastric cancer tissues, we performed immunohistochemical analysis using gastric cancer tissue microarrays (TMAs)." (PMID 39866240, 2025). "KHSRP is significantly upregulated in gastric cancer tissues and is highly correlated with the malignancy of the tumor." (PMID 39866240, 2025). "This study aims to investigate the role of KHSRP in gastric cancer stem cells and tumor metastasis, further elucidating its contribution to gastric cancer growth and uncovering its potential molecular mechanisms." (PMID 39866240, 2025). "KHSRP expression in gastric cancer tissues and normal tissues was analyzed using data from The Cancer Genome Atlas (TCGA) database." (PMID 39866240, 2025). "This study aims to explore KHSRP expression in gastric cancer and its potential effects on tumor progression and immune response." (PMID 39866240, 2025). "The CCK8 assay revealed that KHSRP knockdown significantly inhibited the viability and proliferation of gastric cancer cells." (PMID 39866240, 2025). "The results demonstrated that KHSRP expression was significantly higher in gastric cancer tissues compared to normal gastric mucosa, as indicated by elevated staining scores." (PMID 39866240, 2025). "While KHSRP’s role has been studied in other cancers, its specific involvement in gastric cancer remains poorly understood." (PMID 39866240, 2025). "KHSRP was found to be overexpressed in gastric cancer tissues compared to normal tissues, with a positive correlation to tumor stage and a negative correlation with patient prognosis." (PMID 39866240, 2025). "To further elucidate the role of KHSRP in gastric cancer cells, we used lentiviral vectors to transduce three different shRNAs (shKHSRP-1, shKHSRP-2, and shKHSRP-3) into HGC27 and MKN-45 cells." (PMID 39866240, 2025). "We then investigated the effects of KHSRP knockdown on cell proliferation, tumor stem cell self-renewal, and the invasion and migration capabilities of gastric cancer cells." (PMID 39866240, 2025). "Functional assays revealed that KHSRP promotes gastric cancer cell proliferation, enhances cancer stem cell properties, and increases migratory capabilities in vitro." (PMID 39866240, 2025). "The results showed that KHSRP markedly enhanced the self-renewal capacity of gastric cancer stem cells." (PMID 39866240, 2025).
gastric cancer (continued). "Reports on the role of KHSRP in gastric cancer are limited, particularly regarding its involvement in cancer stem cell maintenance, metastasis, and anti-tumor immunity." (PMID 39866240, 2025). "Transwell assays further confirmed that KHSRP knockdown significantly suppressed the migration and invasion capacities of gastric cancer cells." (PMID 39866240, 2025). "This study highlights the role of KHSRP in enhancing the self-renewal capacity of gastric cancer stem cells while weakening anti-tumor immunity, thereby driving tumor progression and positioning KHSRP as a potential prognostic marker for gastric cancer patients." (PMID 39866240, 2025). "Additionally, KHSRP expression was elevated in gastric cancer tissues compared to adjacent normal tissues and was significantly correlated with tumor stage, lymph node metastasis, and distant metastasis." (PMID 39866240, 2025). "Immunohistochemistry was performed to evaluate KHSRP expression in gastric cancer tissues." (PMID 39866240, 2025). "Our study identifies KHSRP as a potential marker for gastric cancer stem cells and suggests that targeting KHSRP may help eliminate these CSCs, thereby inhibiting the malignant progression of gastric cancer." (PMID 39866240, 2025). "In vivo experiments further revealed that KHSRP silencing markedly increased the infiltration of CD4+, CD8+, Granzyme B+, IFN-γ+, and TNF-α+ cells within the tumor, suggesting that KHSRP could serve as a potential prognostic marker and therapeutic target for gastric cancer." (PMID 39866240, 2025). "We then assessed the impact of KHSRP overexpression on cell proliferation using CCK8 assays, which revealed a significant promotion of cell proliferation in gastric cancer cells." (PMID 39866240, 2025). "To elucidate the role of KHSRP in gastric cancer, we generated HGC27 and MKN-45 cell lines with overexpressed KHSRP." (PMID 39866240, 2025). "The results showed that KHSRP expression was elevated in gastric cancer tissues compared to adjacent non-cancerous tissues." (PMID 39866240, 2025). "In addition, we collected clinical samples and conducted Western blot analysis to confirm KHSRP expression in gastric cancer and adjacent non-cancerous tissues." (PMID 39866240, 2025).
glioma (5 papers, 2015 to 2025). A benign or malignant brain and spinal cord tumor that arises from glial cells (astrocytes, oligodendrocytes, ependymal cells). "For instance, in human glioma cells, KHSRP has been shown to have no significant impact on cell proliferation; however, its low expression can promote tumor formation." (PMID 39866240, 2025).
pancreatic cancer (5 papers, 2013 to 2025). "The present study reports that KHSRP promotes invasiveness and metastasis of pancreatic cancer cells." (PMID 32010427, 2020). "KHSRP was localized in cytoplasmic RNA granules in pancreatic cancer cells, and RNA immunoprecipitation-sequencing analysis showed that the majority of enriched RNAs that immunoprecipitated with KHSRP were small nucleolar RNAs (snoRNAs)." (PMID 32010427, 2020). "Our results provide insight into the link between KHSRP-bound snoRNAs and invasiveness and metastasis of pancreatic cancers." (PMID 32010427, 2020). "Suppression of KHSRP by small interfering RNA decreased the number of cell protrusions and inhibited invasiveness and metastasis of pancreatic cancer cells." (PMID 32010427, 2020). "KHSRP was localized in the nucleus and cell protrusions of pancreatic cancer cell lines." (PMID 32010427, 2020). "Levels of two other known regulators of let-7 biogenesis, KHSRP (positive regulator) and hnRNP-A1 (negative regulator), were not notably different between the various pancreatic cancer cell lines tested and HPDE." (PMID 23335963, 2013).
viral infection (5 papers, 2015 to 2025). "KHSRP as an RNA-binding protein is involved in pre-mRNA splicing, viral infections, neurons, lipid metabolism, cancer, etc." (PMID 40389408, 2025). "Expression of KHSRP was not responsive to H5N1 infection but had a strong induction after H9N2 infection, suggesting that it plays a potential role in the replication and pathogenesis of low pathogenic H9N2 virus infection." (PMID 25557928, 2015).
liver cancer (4 papers, 2012 to 2025). An epithelial or non-epithelial malignant neoplasm that arises from the liver. "It has been reported that KHSRP promotes cell motility in human liver cancer and osteosarcoma cells, and promotes cell proliferation, but not migration, in small cell lung cancer cells." (PMID 29254151, 2017). "Further evidence is presented by KHSRP regulating transcription and mRNA processing which was shown to support migration in liver cancer cells." (PMID 23443080, 2012). "In contrast, in liver cancer, KHSRP has been found to have varying effects." (PMID 39866240, 2025). "However, some studies have found that KHSRP plays an opposite role in liver cancer." (PMID 31775888, 2019).
melanoma (4 papers, 2019 to 2025). A malignant, usually aggressive tumor composed of atypical, neoplastic melanocytes. "Therefore, as previously introduced and discussed in prior research, K-homology-type splicing regulatory protein (KSRP or KHSRP) continues to remain an attractive area of study as a potential therapeutic target for melanoma due to its role in tumor cell growth and migration." (PMID 40699755, 2025). "KH-type splicing regulatory protein (KSRP) has also been found to be essential for melanoma cell proliferation in cells with and without acquired resistance to vemurafenib, a B-raf proto-oncogene (BRAF) kinase inhibitor." (PMID 40872475, 2025). "In agreement with our hypothesis, in silico ChIP-seq analyses identified occupancy of MITF at proximal E box containing promoter sequences of FUBP2 (KHSRP) in primary melanocytes and melanoma cell lines." (PMID 30651597, 2019).
neuroblastoma (4 papers, 2013 to 2023). Neuroblastoma (NB) is the most common solid, extracranial childhood tumor. "We also identify circARID1A as a neuroblastoma-associated circRNA maintaining neuroblastoma cell viability and growth at least partially through its interaction with KHSRP." (PMID 37402719, 2023). "KHSRP and circARID1A expression were positively correlated in neuroblastoma samples from all risk groups in our cohort (r = 0.45)." (PMID 37402719, 2023). "We present evidence for an essential interaction between circARID1A and KHSRP in neuroblastoma cells that impacts cell growth and survival." (PMID 37402719, 2023). "An essential circRNA derived from the ARID1A tumor suppressor gene was identified that uses the KHSRP RBP to promote neuroblastoma cell growth." (PMID 37402719, 2023). "KHSRP expression was higher in RNA sequencing data from our neuroblastoma cohort, compared with publicly available RNA sequencing datasets from other cancers or normal brain tissue." (PMID 37402719, 2023). "The mouse neuroblastoma (N2a) and SD rats are treated with LPS and MnCl2 to evaluate the expression of KHSRP and NLRP3." (PMID 36362011, 2022). "We demonstrate that circARID1A binds to the KHSRP RBP in neuroblastoma cells." (PMID 37402719, 2023). "Furthermore, we also demonstrated that MCC950 was able to down-regulate the KHSRP effect in N2a (neuroblastoma) cells as well as in rat brain in vivo." (PMID 36362011, 2022). "Moreover, the Mn-induced NLRP3-CASP1 inflammasome pathway in mouse neuroblastoma (N2a) cells (250, 500, and 1000 μM Mn for 24 h and 48 h) and Mn-exposed male SD rats (25 mg/kg Mn, 30 days) mediates KH-type splicing regulatory protein (KHSRP) expression." (PMID 38132161, 2023). "Similar to circARID1A knockdown, KHSRP knockdown in IMR-5 cells (validated on RNA and protein levels) reduced cell viability and proliferation, substantiating the proposed functions for KHSRP in neuroblastoma cells." (PMID 37402719, 2023).
Obesity (4 papers, 2020 to 2025). Accumulation of substantial excess body fat. "It has been reported that there is a potential association between the changes in KHSRP function or expression and disorders such as obesity, T2DM and cancer." (PMID 40572705, 2025). "KHSRP is also implicated in several cellular processes associated with neuromuscular diseases, obesity, type II diabetes, and cancer." (PMID 39866240, 2025). "Furthermore, KHSRP is involved in the pathophysiological regulation of neuromuscular disorders, obesity, type II diabetes mellitus, and cancer." (PMID 39439895, 2024).
osteosarcoma (4 papers, 2017 to 2025). A usually aggressive malignant bone-forming mesenchymal neoplasm, predominantly affecting adolescents and young adults. "Among these proteins, immunohistochemistry confirmed the overexpression of KH-type splicing regulatory protein (KSRP) in osteosarcoma biopsy samples." (PMID 36077137, 2022). "KHSRP knockdown in osteosarcoma cell U2OS significantly upregulates cell proliferation." (PMID 29020972, 2017).
prostate carcinoma (4 papers, 2017 to 2024). A carcinoma that arises from epithelial cells of the prostate gland. "To pursue the probability of an correlation between KHSRP SUMOylation and prostate cancer, we further extracted data from the database of “The Cancer Genome Atlas Research Network” (TCGA)." (PMID 29020972, 2017). "Since KHSRP acetylation significantly affects the tumor growth ability of prostate cancer cells, we tried to verify whether KHSRP acetylation is variated in PCa tissue samples." (PMID 38501452, 2024). "The data of KHSRP expression levels together with the associated clinical data revealed that the KHSRP expression levels for 435 prostate cancer patients was not related to Gleason score (Pearson correlation with r value = 0.056; P = 0.242)." (PMID 29020972, 2017). "But among 212 prostate cancer patients with high expression levels of KHSRP (median value >8732 FPKM), the expression levels of Ubc9, which is only E2 conjugating enzyme for SUMOylation, was positively correlated with Gleason score (Pearson correlation with r value = 0.147*; P = 0.033)." (PMID 29020972, 2017). "KHSRP deacetylated by SIRT7 feasibly decays mRNAs of DNA damage response (DDR) genes to weaken DNA repair ability, resulting in prostate cancer (PCa) cell death." (PMID 38501452, 2024).
Hepatic fibrosis (3 papers, 2021 to 2024). The presence of excessive fibrous connective tissue in the liver. "For example, decreased miR-27b can ameliorate Schistosoma japonicum-caused liver fibrosis by the upregulation of KH-type splicing regulatory protein (KSRP), and KSRP can promote stabilization of TGF-β1." (PMID 34521449, 2021). "Notably, we detected reduced expression of KHSRP, which has been reported as a splicing factor and shows altered expression levels in nonalcoholic fatty liver disease (NAFLD), hepatocellular carcinoma (HCC), and schistosome-induced hepatic fibrosis." (PMID 39187547, 2024).
liposarcoma (3 papers, 2017 to 2024). A usually painless malignant tumor that arises from adipose tissue. "SMN also binds to fragile X mental retardation protein (FMRP), KH-type splicing regulatory protein (KSRP) and fused in sarcoma/translocated in liposarcoma (FUS/TLS), which are important for miRNA biogenesis and function." (PMID 28522960, 2017). "In addition, SMN protein binds to miR processing proteins including fragile X mental retardation protein, KH-type splicing regulatory protein, and fused in sarcoma/translocated in liposarcoma." (PMID 36604149, 2023).
small cell lung carcinoma (3 papers, 2017 to 2025). Small cell lung cancer (SCLC) is a highly aggressive malignant neoplasm, accounting for 10-15% of lung cancer cases, characterized byrapid growth, and early metastasis. "KHSRP has been reported to predominantly induce cell proliferation in small cell lung cancer cells by promoting maturation of miR-26a and inhibiting the expression of its target, PTEN." (PMID 29254151, 2017).
papillary thyroid carcinoma (2 papers, 2022 to 2025). "For example, lncAB bound KH-type splicing regulatory protein (KHSRP) and also decreased the expression of KHSRP in papillary thyroid carcinoma, thus increasing CDKN1a (p21) expression and decreasing CDK2 expression to repress cell proliferation." (PMID 36267418, 2022). "Similarly, in papillary thyroid carcinoma, the lncRNA AB074169 interacts with KHSRP protein to downregulate its expression and inhibit cell proliferation." (PMID 40416600, 2025).
breast tumors (1 paper, 2025). "Simultaneously, we exhibited that SB-T-101141 triggered a novel ferroptosis to repress breast tumor growth by stably binding to KHSRP to inhibit the expression of CISD1 related to iron homeostasis." (PMID 40389408, 2025). "Likely, the increased lipid peroxidation product, aldehyde 4-HNE, was diminished in KHSRP-depleted xenografted breast tumors." (PMID 40389408, 2025). "More importantly, we employed the xenografted mice and found that although knocking down KHSRP inhibited breast tumor growth, the tumor growth inhibition effect from SB-T-101141 was also abolished in KHSRP-depleting cells, indicating that KHSRP acts as at least one of the targets of SB-T-101141." (PMID 40389408, 2025).
Fanconi anemia (1 paper, 2024). Fanconi anemia (FA) is a hereditary DNA repair disorder characterized by progressive pancytopenia with bone marrow failure, variable congenital malformations and predisposition to develop hematological or solid tumors. "However, KEGG enrichment analysis of differentially expressed mRNA transcripts suggested that KHSRP acetylation‐associated genes were significantly enriched in clusters of Homologous recombination, Mismatch repair, Base excision repair, or Fanconi anemia." (PMID 38501452, 2024).
gastric tumors (1 paper, 2025). "Additionally, KHSRP expression was particularly high in poorly differentiated gastric tumors." (PMID 39866240, 2025).
injury (1 paper, 2025). Damage inflicted on the body as the direct or indirect result of an external force, with or without disruption of structural continuity. "One such RBP, the RNA binding protein KHSRP, is locally translated following nerve injury, promotes decay of other axonal mRNAs, and slows axon regeneration." (PMID 40924015, 2025).
laryngeal squamous cell carcinoma (1 paper, 2017). A squamous cell carcinoma that arises from the larynx. "However, in contrast to our findings, several studies have revealed suppressive effects of KHSRP on EMT in murine immortalized mammary epithelial cells and laryngeal squamous cell carcinoma cells." (PMID 29254151, 2017).
liver disease (1 paper, 2024). "Our results highlight the protective role of KHSRP in liver disease and illuminate the links between KHSRP, pre-mRNA splicing, and liver injury." (PMID 39187547, 2024). "Dysregulation of KHSRP in liver disease has been previously reported; however, the role of KHSRP in ALF remains unclear." (PMID 39187547, 2024).
schizophrenia (1 paper, 2012). A major psychotic disorder characterized by abnormalities in the perception or expression of reality. "Besides categories related to hematological function, the Tan schizophrenia module was also enriched for the Neurological Disease category (CCL5, PRKCQ, PTAFR, AKR1B1, CD247, IL10RA and KHSRP)." (PMID 22761806, 2012).
squamous cell carcinoma (1 paper, 2017). A carcinoma arising from squamous epithelial cells. "A similar pattern of KHSRP immunoreactivity was observed in squamous cell carcinomas of other tissues." (PMID 29254151, 2017).
stomach adenocarcinoma (1 paper, 2025). "Notably, KHSRP expression was significantly elevated in stomach adenocarcinoma (STAD)." (PMID 39866240, 2025).
triple-negative breast carcinoma (1 paper, 2019). An invasive breast carcinoma which is negative for expression of estrogen receptor (ER), progesterone receptor (PR), and human epidermal growth factor receptor 2 (HER2).